EGFR (epidermal growth factor receptor)
Diseases named in the same sentence as EGFR in open-access papers (continued):
Sharing a sentence is not in itself a finding about the gene and the disease.
cancer (continued). "Understanding how ZNRF3/RNF43 regulates EGFR and the crosstalk between EGFR and WNT receptors may offer potential therapeutic targets for cancer treatment." (PMID 38260423, 2024). "For example, DSF can inhibit cancer growth by inhibition of the p97–NPL4–UFD1 complex controlling protein homeostasis, as well as several other cellular pathways including ROS, PIK, MAPK, NF-κB, ALDH, EGFR/Src/VEGF." (PMID 38657866, 2024). "metMHN also infers multiple positive interactions between gene mutations and corresponding copy number alterations, exemplified by the interaction between EGFR (M) and amplification of EGFR/7p, as well as between STK11 (M) and deletion of STK11/19p—a pattern commonly seen across various cancers." (PMID 38940126, 2024). "Cancer therapy utilizing EGFR inhibitors has fewer negative effects since it primarily and exclusively kills cancer cells." (PMID 38443456, 2024). "In veterinary medicine, EGFR and ERBB2 have been reported in dogs and cats with cancer." (PMID 39126006, 2024). "Histogram analysis of genome-wide EGFR correlation values integrating the position of GCLC gene highlights the shift of GCLC and EGFR correlation value in normal brain tissue vs. cancer tissue." (PMID 39001381, 2024). "In HT1080 and U87MG cancer cells, the CD44s isoform of CD44 predominantly expressed in these cells interacts with Rab7A in the late-endosome/lysosome compartments, reduces levels of the GTP-bound form of Rab7A, and inhibits the Rab7A-mediated EGFR degradation." (PMID 39594667, 2024). "Epidermal growth factor receptor (EGFR) and phosphatidylinositol 3-OH kinase (PI3K) emerge as potential cotargeting candidates to test this concept because these oncogenic kinases drive adaptive resistance across a broad spectrum of human cancers." (PMID 38992135, 2024). "Rab coupling protein (RCP), a pivotal player in cancer invasion, promoted β1 integrin expression, which led to the phosphorylation of FAK and subsequent activation of the epidermal growth factor receptor (EGFR), thereby driving OC cell invasion." (PMID 39678497, 2024). "However, EGFR, which is downregulated upon KMT9 knockdown in 5637 and CAL-29 cells, has emerged as a prognostic factor in various cancer types, including BC." (PMID 38672614, 2024). "EGFR can directly participate in regulating the transcription of target genes as a transcription factor, and the mesenchymal-epithelial transition factor (MET) is closely related to the malignant phenotype of cancer cells." (PMID 39022612, 2024). "The EGFR signaling pathway enhances SCAP N-glycosylation to deactivate SREBP-1 by promoting glucose uptake, and SREBP-1 can promote the progressive metastasis of cancer." (PMID 38319706, 2024). "In fact, in other contexts, overexpression of Rab11a has been shown to contribute to the proliferation and invasion of cancer cells via increased signaling of ERK, PI3K/AKT, EGFR, WNT, and MMP2, consistent with our findings that increased Rab11 activity can drive angiogenesis." (PMID 38903077, 2024). "In addition, while the targeting of EGFR and integrin is a valid therapeutic strategy, it is the downstream signaling pathways, particularly PI3K/AKT/mTOR and MAPK, that drive cancer progression and therapeutic resistance." (PMID 39126121, 2024). "Moreover, CD8+ T cell-derived exosomes tethered with both anti-epidermal growth factor receptor (EGFR) antibodies and IL-2 via MTFP specifically induced EGFR-positive cancer cell death through immune activation." (PMID 38172594, 2024). "By identifying ZNRF3/RNF43 as crucial regulators linking EGFR and WNT signaling at the membrane receptor level, our work reveals a novel mechanism of EGFR and WNT coactivation, which is commonly observed in human cancers." (PMID 38260423, 2024). "Although the role of this nuclear importinin endothelial cells remains relatively unexplored, it has garneredattention as a negative EGFR regulator in cancer and has been foundto be deleted or downregulated in certain cancer types." (PMID 38809962, 2024).
cancer (continued). "The second cluster of DEGs, including FGFR2, KDR2 and MET, indicates the importance of key cancer-related pathways, including the PI3K-Akt signaling pathway, EGFR tyrosine kinase inhibitor resistance pathway, Rap1 signaling pathway, Ras signaling pathway, and MAPK signaling pathway." (PMID 38166892, 2024). "Most of these anti-cancer targets cover PD-1, PD-L1, CTLA4, HER2, EGFR, and BCMA." (PMID 38254860, 2024). "The use of anti‐EGFR antibody for EGFR‐amplified cancers has been promising; however, the evidence is not yet clear." (PMID 39540676, 2024). "The epidermal growth factor receptor (EGFR) family, a group of molecular targets including EGFR (also known as human epidermal growth factor receptor 1, [HER1]), HER2, HER3, and HER4 play a role in the growth and survival of cancer cells." (PMID 39239273, 2024). "In addition, cancer cell-derived EVs carrying c-Myc, ZIP4, or an active form of epidermal growth factor receptor (EGFR) promote their own proliferation in an autocrine manner." (PMID 38796692, 2024). "Remarkably, our study unexpectedly discovered that KRAS G12C–mutant cancer cells, whether they exhibit intrinsic or acquired resistance to KRAS G12C inhibitors, also display cross-resistance to other inhibitors targeting EGFR, IGF1R, MEK, or SHP2." (PMID 39704172, 2024). "Cell membrane proteins (CD133, CD147, and CD44) and membrane receptors such as transferrin receptor, epidermal growth factor receptor-EGFR, human epidermal growth factor receptor 2-HER2, and human B-cell antigen, CD20, are the commonly used antibodies for cancer cells targeting." (PMID 39598500, 2024). "In addition, various tyrosine kinase receptors closely related to HER2, including EGFR, have been shown to regulate VGSC expression in carcinoma cells." (PMID 39048659, 2024). "Fu confirmed this observation in a study with dogs with nasal carcinomas including EGFR-negative carcinomas." (PMID 39268521, 2024). "The overexpression of epidermal growth factor receptor (EGFR) in more than 90% of HNSCC patients led to the approval of cetuximab (Erbitux), a monoclonal antibody targeting EGFR, in combination with radiation therapy for advanced local/regional carcinoma." (PMID 38526631, 2024). "In addition to its effect on apoptosis and the cell cycle, compound 6b appeared to inhibit various kinases, such as CDK2, EGFR, HER2, and VEGFR2, which are overexpressed in cancer cells." (PMID 36678593, 2023). "Unlike cytostatic TKIs against the EGFR, the allosteric degraders of the EGFR affect cell survival rather than growth and induce cancer cell death like cytotoxic molecules." (PMID 37754201, 2023). "EGFR or HER1 is a receptor tyrosine kinase that activates oncogenic signaling pathways including rat sarcoma virus (Ras)/MAPK, PI3K/Akt, and phospholipase C (PLC)/PKC, and drives cancer cell growth, survival, and invasion." (PMID 37457288, 2023). "Second, we did not specifically investigate EGFR-mutant cancers and are thus unable to draw conclusions regarding this group." (PMID 37088795, 2023). "Although the bioconjugates were useful in identifying and sorting cancer cells, they were unable to perform these functions in the case of K562 cells because they lacked surface expression of human epidermal growth factor receptor (EGFR)." (PMID 36840008, 2023).
cancer (continued). "The first one, obtained from the Cancer Imaging Archive (TCIA), consisted of 60 cases (25% EGFR, 23% KRAS); the second one, provided by the Azienda Ospedaliero-Universitaria ’Ospedali Riuniti’ of Foggia, was composed of 55 cases (16% EGFR, 28% KRAS)." (PMID 37508774, 2023). "As an EGFR tyrosine kinase inhibitor, GFT disrupts EGFR signaling and thus leads to the inhibition of cell proliferation, migration, and survival and the inducement of apoptosis in cancer cells." (PMID 38004415, 2023). "Overall, these studies indicate that EGFR in CAFs is likely not the only key player, so it cannot be considered an independent prognostic factor for survival evaluation in patients with cancer." (PMID 38006033, 2023). "Although the exact role of anoctamin-1 in cancer is unknown, it participates in cancer proliferation and migration by modulating the activity of the MAPK, CAMKII, and EGFR signaling pathways." (PMID 37749499, 2023). "We also demonstrated the inability of the bispecific Nanofitin to use the pre-anchoring activity in low EGFR expressing cells despite the high levels of PDL1, which support its selectivity for cancer cells with moderate to high levels of EGFR et PDL1 and a lack of engagement of healthy cells." (PMID 37189383, 2023). "These proteins have different types of substrates, including cancer-related proteins, such as NOTCH receptor and ligand, epidermal growth factor receptor (EGFR) ligand, interleukin-6 receptor (IL-6R), tumor necrosis factor (TNF) and its receptor, E-cadherin and CD44." (PMID 37370817, 2023). "Other factors, such as smoking status, T stage, recurrence, age over 80 years old, synchronous with other cancer, EGFR status, and pathological type, did not indicate significant differences in overall survival." (PMID 36653333, 2023). "MT4-MMP was validated as a key signaling precursor and partner of EGFR, which enhances its activation leading to cancer cell proliferation in a non-proteolytic manner." (PMID 37373092, 2023). "The EgA1 anti-EGFR nanobody was used for constructing LiTE (light T-cell engager) and ATTACK (asymmetric tandem trimerbody for T-cell activation and killing cancer) bispecific engagers by combining one and three EGFR-binding nanobodies with a single CD3-binding scFv, respectively." (PMID 36761751, 2023). "The receptor tyrosine kinase EGFR regulates the activity of pro-oncogenic pathways including the mitogen activated protein kinases (MAPKs) ERK1/2 and mammalian target of rapamycin (mTOR), which both promote cancer cell proliferation." (PMID 37696458, 2023). "The enrichment network diagram of related genes showed that the enrichment network includes PI3K-Akt signaling pathway, EGFR tyrosine kinase inhibitor resistance, TGF-beta signaling pathway, senescence and autophagy in cancer and cytokine signaling in immune system." (PMID 37808589, 2023). "While the EGFR, HER2, and HER3 stimulate cancer proliferation, the role of HER4 is more complex." (PMID 37508387, 2023). "Being aware that numerous EGFR inhibitors had been previously discovered as modifiers of ABCB1 and/or ABCG2, we explored the potential of furmonertinib to enhance chemosensitivity in multidrug-resistant cancer cells that overexpress ABCB1 or ABCG2." (PMID 37762275, 2023). "This type of acquired resistance has been seen in lung tumors, where resistance to EGFR inhibitors (EGFRi) was associated with compensatory up-regulation of HER3, and combining EGFR and HER3 inhibitions led to improved anti-cancer effects compared to EGFRi alone." (PMID 37163206, 2023). "Collectively, our findings indicate that the concomitant overexpression of both EGFR, CBX3 and RAC1 may be an extremely unfavorable general prognosis marker in human cancer." (PMID 37633946, 2023).
cancer (continued). "In a mouse model of RCC, lenvatinib treatment inhibits both EGFR and FGFR signaling, and could restore the IFNγ-STAT1 signaling pathway and consequently prove the anti-cancer effect of the inhibitor." (PMID 37190141, 2023). "Although EGFR is one of the important targets for cancer therapy, anti-mEGFR mAbs for preclinical study have not been developed." (PMID 37489364, 2023). "Including agents that target EGFR, PDGFR, and FGFR in anti-VEGF therapy can also improve the efficacy of cancer treatment by rewiring multiple cellular pathways and minimizing drug resistance in ovarian and other cancers." (PMID 36831623, 2023). "MCF7, HEPG2, and NCIH460 cancer cells, as well as kidney cells (HEK293) expressing EGFR and MET receptors, were subjected to varying concentrations (62.5, 125, 250, and 500 μg/mL) of SPIONs, BS-S, BS-SPP, and Butein to predict its cytotoxic effect by MTT dye reduction assay." (PMID 37631372, 2023). "Our results conclude that β-sitosterol conjugated with SPION, PEG, and PNIPAM could be a potential targeted therapy in inhibiting EGFR and MET receptor-expressing cancer cells." (PMID 37631372, 2023). "The epidermal growth factor (EGF) receptor (EGFR, ErbB-1, HER1) is expressed in many tissues and has many functions during development, in healthy people and in several pathological conditions, including cancer." (PMID 37442828, 2023). "Recent studies have shown the promise of ferroptosis-inducing therapy in EGFR-TKI resistant cancer, but have not been translated into clinical benefits." (PMID 36760347, 2023). "In solid tumors, the high essentiality of EGFR and ERBB2 may suggest that these genes are highly important to the viability of cancer cells in their respective solid tumor indications." (PMID 37835579, 2023). "ZD6474, a co-inhibiter of VEGFR/EGFR and mTOR kinases, is also illustrated substantially higher anti-proliferative activity than either VEGFR inhibitor or EGFR inhibitor alone applied in cancers." (PMID 36227401, 2023). "Indeed, the EGFR and ERBB families (ERBB2, ERBB3 and ERBB4) were also ranked in the top 10 cancer driver targets in the transcriptional networking, suggesting their roles in uPAR-mediated tumorigenesis processes were highly anticipated." (PMID 37895906, 2023). "Targeting m6A modifications of oncogenes such as EGFR and MYC can significantly suppress their expression and the proliferation of cancer cells; demethylating metabolic gene PDK4 can reduce its expression and glycolysis of cancer cells." (PMID 36260366, 2023). "Overexpression of WNT5a could inhibit the progression of EGFR mutant NSCLC by blocking the canonical WNT pathway, indicating that WNT5a plays an anti-cancer role in the development of such NSCLC." (PMID 37486552, 2023). "A carefully designed proof-of-principle study demonstrated that CAR-T EVs with EGFR and HER-2 specific CAR efficiently and specifically kill HER2+ and EGFR+ cancer cells in mouse xenograft models, without impacting cells that do not express those molecules." (PMID 36831396, 2023). "EGF/EGFR activation results in the separation of SHC‐binding protein 1 (SHCBP1) from SHC adaptor protein 1 (SHC1), which then translocates to the nucleus and promotes cancer development via multiple signaling pathways." (PMID 38107059, 2023). "The representative first-generation EGFR-TKI (tyrosine kinase inhibitor) gefitinib induces apoptotic cell death via the intracellular Ca2+ and ROS release, the upregulating of Nox2 or Nox4, and the ER stress response in various cancer cell types." (PMID 36768961, 2023). "However, upon activation of epidermal growth factor (EGF) receptor (EGFR), PKM2 can translocate into the nucleus in a form of dimer and serve as a transcription coactivator or protein kinase in cancer cells." (PMID 36899022, 2023).
cancer (continued). "HER2 is part of the epidermal growth factor receptor (EGFR/Erb) family of tyrosine kinase receptors, which consists of four members-EGFR/HER1/ErbB1, HER2/ErbB2, HER3/ErbB3, and HER4/ErbB4-and is closely related to cell proliferation, differentiation, migration, and cancer development." (PMID 36937848, 2023). "Notably, in NSCLC tumors that develop EGFR-TKI refractory disease, CD70 is upregulated by refractory cancer cells." (PMID 37545491, 2023). "In the absence of E-Cad, cancer cells undergo increased activation of the epidermal growth factor receptor (EGFR)." (PMID 36671501, 2023). "Clinical-patient data from the GEO databases revealed that JWA mRNA expression had no obvious correlation with EGFR expression in cancer." (PMID 37240137, 2023). "The EGFR and HER 2, which are of the same family (HER/EGFR/ERBB), share a high degree of structural and functional homology and play an important role in pathogenesis of several cancers via cell proliferation, survival, migration, adhesion, differentiation, angiogenesis, invasion, and metastasis." (PMID 38186572, 2023). "Additionally, EGFR-mediated Signal Transduction and Transcription Factor 3 (STAT3) signaling activation promote cell proliferation and glycolysis in various cancers." (PMID 37944197, 2023). "Specific oncogenic kinase targets including epidermal growth factor receptor (EGFR) and vascular endothelial growth factor receptor (VEGFR) were involved in the invasion and metastasis of malignant tumors (Hanahan and Weinberg., 2011; Kittler and Tschandl, 2018)." (PMID 37153777, 2023). "Importantly, the CCA-specificity of ICAM1 is higher than many common cancer targets such as ROR1, HER2, EGFR, VEGFR, and P-selectin." (PMID 37717087, 2023). "Genomic and proteomic mutation analysis is the standard of care for selecting candidates for therapies with tyrosine kinase inhibitors against the human epidermal growth factor receptor (EGFR TKI therapies) and further monitoring cancer treatment efficacy and cancer development." (PMID 36865093, 2023). "The risk stratification machine learning model using Logistic regression (L1 regularization) combining morphological parameters and molecular markers-αvβ6, EGFR, CD17, McM2, geminin, and Ki-67 differentiated cancer and HGD from LRL with sensitivity and specificity of 78% and 88% respectively." (PMID 37747904, 2023). "Additionally, the overall phosphorylation assay identified 6 upregulated phosphorylated proteins in cancer related pathways such as HIF-1, PI3K-Akt, EGF/EGFR, Toll-like receptor, and JAK-STAT signalling." (PMID 38102712, 2023). "We assessed NPIIAGG and dN/dSPW levels of six major cancer-related pathways which form two strongly connected gene networks: (i) pathways of AKT, mTOR, and EGFR signaling, and (ii) Notch, WNT, and Hedgehog pathways relative to the whole set of 2972 molecular pathways under study." (PMID 37174700, 2023). "It seems that cancers expressing wild-type EGFR do not respond to TKIs regardless of the expression level of EGFR." (PMID 37446288, 2023). "In this study, we demonstrated that afatinib, a tyrosine kinase inhibitor that is effective against both HER2 and EGFR, showed an anti-cancer effect for HER2 E401G and its amplification using the cancer models PDX and CTOS derived from a patient tissue specimen." (PMID 36690964, 2023). "In this review, we summarize the protumoral activity of PGE2 inflammatory pathways, mainly focusing on the interplay with the epidermal growth factor receptor (EGFR), and we show the recent advancement in the pharmacological modulation of these signaling pathways in cancer management." (PMID 37190301, 2023). "Similarly, recent work using PDX models showed that EGFR inhibition in CRC tumors induces Paneth-like phenotypic rewiring, suggesting that cellular plasticity is shaping drug response in cancer." (PMID 38047086, 2023).